KCTD12 (potassium channel tetramerization domain containing 12)
Diseases named in the same sentence as KCTD12 in open-access papers (continued):
Sharing a sentence is not in itself a finding about the gene and the disease.
ovarian carcinoma (1 paper, 2025). A malignant neoplasm originating from the surface ovarian epithelium. "Further studies are needed to clarify the role of KCTD12 and its mutations in the pathophysiology, chemoresistance, and progression of ovarian cancer." (PMID 40771481, 2025). "Given the similarities between GIST and epithelial ovarian cancers in the acquisition of aggressive features such as invasion, metastasis, and peritoneal dissemination, it is plausible that KCTD12 mutations could lead to a loss of the tumor suppressive function of Pfetin." (PMID 40771481, 2025).
Seizure (1 paper, 2017). A seizure is an intermittent abnormality of nervous system physiology characterized by a transient occurrence of signs and/or symptoms due to abnormal excessive or synchronous neuronal activity in the brain. "Seizure susceptibility and ethanol consumption were also investigated in a KCTD12 knockout mouse model." (PMID 28713569, 2017).
serous ovarian carcinoma (1 paper, 2018). "In a genome-wide mutation screening, a mutation of KCTD12 has been reported in a case of high-grade serous ovarian carcinoma." (PMID 29930747, 2018).
testicular germ cell tumor (1 paper, 2023). A germ cell tumor arising from the testis. "The expression of KCTD12 in CESC, PAAD, STAD, testicular germ cell tumors (TGCT), THYM, and HNSC (HNSC-HPV−/HNSC-HPV+) TCGA tumors showed a statistically positive correlation with the degree of CAF infiltration." (PMID 37626178, 2023).
viral infection (1 paper, 2019). "For instance, 4 viral infection FUs and one immunological disorder FU are all enriched among the predicted targets of the BTB/POZ domain-containing protein KCTD12, an enigmRBP22." (PMID 30867517, 2019).
cancer (15 papers, 2016 to 2025). A tumor composed of atypical neoplastic, often pleomorphic cells that invade other tissues. "KCTD12 is deregulated in a variety of different cancer types and associated with cancer malignancy, tumorigenicity, and stemness." (PMID 41451080, 2025). "Second, we analyzed the infiltration of CD8+ and CD4+ T cells and cancer-associated fibroblasts in tumors and explored the correlation between KCTD12 expression and tumor cell stemness, genomic heterogeneity, and diagnostic specificity." (PMID 37626178, 2023). "Data from the cBioPortal for cancer genomics showed that the protein encoded by KCTD12 contained 325 amino acids with 15 missense and two truncated mutations." (PMID 37626178, 2023). "To explore the mechanisms of action underlying the effects of KCTD12 in cancer, we performed immunoprecipitation coupled with liquid chromatography tandem mass spectrometry (LC-MS) to identify its interacting proteins." (PMID 28869606, 2017). "Our findings strongly suggest that KCTD12 may be a useful diagnostic biomarker for these cancers." (PMID 28869606, 2017). "Several of the hits including MAGED1 and KCTD12 have been described in both cancer context and general cellular processes." (PMID 40193385, 2025). "The present study revealed a correlation between the KCTD12 gene and pan-cancer, indicating an important role for KCTD12 in various tumors through multiple signaling pathways." (PMID 37626178, 2023). "Tumor cell stemness analysis indicated that KCTD12 was negatively correlated with stemness in most malignant tumors, providing evidence that KCTD12 is an oncogene." (PMID 37626178, 2023). "In the present study, the expression of KCTD12 was down-regulated in most tumors, however, the same expression trend of KCTD12 was observed with different outcomes in cancer." (PMID 37626178, 2023). "KCTD12 facilitates M phase entrance and promote cancer cell proliferation which is done by CDK1 dephosphorylation by KCTD12." (PMID 30157793, 2018). "We also found that KCTD12 overexpression not only facilitated the G2/M transition and induced cancer cell proliferation, but also promoted the growth of subcutaneous tumors and Ki-67 proliferation index in mice." (PMID 28869606, 2017). "Here we provide the first evidence indicating that KCTD12 can facilitate cancer cell entry into M phase and promote cell proliferation and tumorigenesis." (PMID 28869606, 2017). "We performed colony formation assay to determine the effects of KCTD12 on cancer cell colony formation ability, the results of which showed that HeLa cells with KCTD12 knockdown formed fewer colonies than negative-control cells." (PMID 28869606, 2017). "Therefore, elevation or decrease of KCTD12 can be used as a sensitive biomarker for the diagnosis of malignant tumors." (PMID 37626178, 2023). "In recent years, several studies reported the role of KCTD12 in malignant tumors." (PMID 37626178, 2023). "Recently, several studies have investigated the role of KCTD12 in cancer." (PMID 37626178, 2023). "To determine whether KCTD12 phosphorylation at serine 200 and serine 243 by Aurora A is required for the cancer-promoting effects of KCTD12, we performed a series of in vitro and in vivo experiments." (PMID 28869606, 2017). "In addition, Aurora A phosphorylated KCTD12 at serine 243, thereby initiating a positive feedback loop necessary for KCTD12 to exert its cancer-promoting effects." (PMID 28869606, 2017). "We next studied the biological function of KCTD12 in cancer cells." (PMID 28869606, 2017). "As chemoresistance is another characteristic of cancer stem cells, we then sought to test whether there is a correlation between KCTD12 level and drug resistance in CRC cells." (PMID 26847701, 2016). "Thus, the role of KCTD12 in cancer remains incompletely understood." (PMID 39334449, 2024). "Phosphorylation by AURKA at Ser243 may account for the cancer-promoting effects of KCTD12." (PMID 33451333, 2021).
cancer (continued). "KCTD12 has also been implicated in several cancers not discussed here." (PMID 31197948, 2019). "Collectively, our results indicated that KCTD12 may play an important role in human cancer." (PMID 28869606, 2017). "Emerging evidence has highlighted the significance of various gene families in cancer progression, including the KCTD family, comprising genes, including KCTD2, KCTD5, KCTD9, KCTD10, KCTD12, KCTD15, KCTD16, and KCTD21." (PMID 40832836, 2025). "Taken together, our study indicates that KCTD12 exerts its effects in cancer by forming a complex with CDC25B and CDK1, and the phosphorylation of KCTD12 at serine 243 is necessary for the interaction of KCTD12 and CDK1, but it is not a crucial factor for the interaction with CDC25B." (PMID 28869606, 2017). "To date, there have been no comprehensive studies on KCTD12 across cancers." (PMID 37626178, 2023). "Abnormal expression of the potassium channel tetramerization domain containing 12 (KCTD12) is closely related to the occurrence and development of various tumors, but a pan-cancer analysis of KCTD12 has not yet been conducted." (PMID 37626178, 2023).
tumor (13 papers, 2016 to 2025). "We further explored the prognostic relationship between KCTD12 mutations and different clinical tumor cases." (PMID 37626178, 2023). "More importantly, high KCTD12 expression was associated with larger tumor sizes, higher pathological stages and poor patient survival." (PMID 28869606, 2017). "KCTD12 showed high diagnostic sensitivity for various types of tumors and may be involved in tumor cell biology by affecting tumor cell stemness, tumor burden, and other characteristics." (PMID 37626178, 2023). "Depending on tumor types, KCTD12 exhibits oncogenic or tumor-suppressive properties and serves as a prognostic biomarker in gastrointestinal tumors." (PMID 40221412, 2025). "For example, KCTD12 was positively correlated with the infiltration of Th2 cells and DC cells, suggesting a potential role in modulating immune responses within the tumor microenvironment." (PMID 40832836, 2025). "KCTD12 overexpression occurs in higher tumor grades in gastrointestinal stromal tumors, but it acts as a tumor suppressor in colon cancer." (PMID 39334449, 2024). "Conversely, a set of genes, namely CLIP4, HAS2, and KCTD12 (p < 0.01), were found to be notably downregulated in tumor cells." (PMID 38549669, 2024). "First, the mRNA and protein levels of KCTD12 were examined and their correlations with tumor stage and survival were explored." (PMID 37626178, 2023). "Recent oncology studies have shown that KCTD12 plays an important role in maintaining stemness and promoting or inhibiting tumor cell proliferation." (PMID 37626178, 2023). "In the four types of tumors explored, the phosphorylation level of KCTD12 at S200 in tumor tissues was significantly lower than that in normal tissues [PAAD (P = 3.99e−03), LUAD (P = 2.65e−13), BRCA (P = 3.01e−03), and HNSC (P = 3.82e−04)]." (PMID 37626178, 2023). "Regarding the role of self-renewal factors such as SOX2, NANOG, KLF4, and SALL4 in biology of tumor cells we assessed the probable role of KCTD12 in regulation of such factors in the levels of mRNA expression." (PMID 30157793, 2018). "To elucidate the tumor suppressor function of pfetin and possible regulatory mechanisms of KCTD12 in GIST further, we employed RNA interference in cultures of GIST T1 cells." (PMID 29930747, 2018). "We have shown that KCTD12 acts as a tumor suppressor in ESCC through different signaling pathways and chromatin remodeling." (PMID 30157793, 2018). "In contrast, only 15.1% of tumor tissues displayed low-to-moderate KCTD12 expression, whereas 60.2% of normal tissues showed low-to-moderate KCDT12 expression." (PMID 28869606, 2017). "More importantly, we noted that patients with high tumor KCTD12 expression levels had significantly shorter survival (median survival=33.0 months) than patients with low tumor KCD12 expression levels (median survival=54.0 months)." (PMID 28869606, 2017). "The chi-square test revealed that the KCTD12 level was strongly related to the clinical stage (p = 0.027), tumor size (p = 0.021) and vital status (p = 0.003)." (PMID 26847701, 2016). "We used GEPIA 2 to explore the relationship between KCTD12 expression and tumor stage." (PMID 37626178, 2023). "In KIRC and KIRP, the expression of KCTD12 decreased with increasing tumor stage (P < 0.05)." (PMID 37626178, 2023). "In addition, the expression of KCTD12 is correlated with RNA modification and negatively correlated with the stemness of various tumors, which can reduce the malignant phenotype of tumor cells." (PMID 37626178, 2023). "Notably, 84.9% (79/93) of tumor tissues showed high KCTD12 expression, whereas only 39.8% (37/93) of normal tissues showed high KCTD12 expression." (PMID 28869606, 2017). "The protein level of KCTD12 was significantly higher in normal tissues than in CRC tumor tissues." (PMID 26847701, 2016). "Moreover, KCTD12 regulates tumor cell stemness characteristics through the ERK pathway." (PMID 37626178, 2023).
tumor (continued). "It was found that the expression level of KCTD12, SIAH1, TRIM58, UBE2S, and UBE2T were significantly decreased in tumor tissue compared with the normal tissue, but TRIM47 was upregulated." (PMID 36534449, 2022). "Our results showed that KCTD12 decreases the cell migration of ESCC cells through TWIST1 and can be introduced as a therapeutic marker against the EMT process and tumor relapse." (PMID 30157793, 2018). "KCTD12 in vitro knockdown resulted in the accelerated growth of GIST T1 cells, confirming that pfetin functions as a tumor suppressor." (PMID 29930747, 2018). "In our study, significant upregulation of Pfetin (KCTD12) was detected in residual tissue from patients with high-grade serous ovarian cancer (HGSOC) who had received neoadjuvant chemotherapy, suggesting a potential role for Pfetin in chemoresistance or tumor aggressiveness." (PMID 40771481, 2025). "Therefore, KCTD12, CDK1, and CDC25B complex play an important role in tumor cell cycle regulation." (PMID 30157793, 2018). "The silencing of endogenous KCTD12 and the overexpression of ectopic KCTD12 dramatically enhances and represses CRC cell stemness, respectively, as assessed in vitro and in vivo using a colony formation assay, a spheroid formation assay and a xenograft tumor model." (PMID 26847701, 2016).
infection (2 papers, 2019 to 2025). The state of being infected such as from the introduction of a foreign agent such as serum, vaccine, antigenic substance or organism. "KCTD12 predicted interactors are enriched among coding transcripts annotated in three FUs related to immune system pathways, suggesting that this novel and uncharacterized RBP may be involved in immunity and in infection-related processes." (PMID 30867517, 2019). "We stress that KCTD12, TF, LTF, and MPO are host-response proteins; their altered serum-exosomal levels mirror the child’s innate reaction to infection with azithromycin-resistant M. pneumoniae and do not reflect or cause the bacterial mutation that directly confers resistance." (PMID 41451080, 2025).
psychiatric disorder (2 papers, 2013 to 2025). A disorder characterized by behavioral and/or psychological abnormalities, often accompanied by physical symptoms. "KCTD12, an auxiliary subunit in GABAB receptor signaling, is implicated in stress response and psychiatric disorders, with stress increasing its expression in the hippocampus, affecting neuronal excitability and stress vulnerability." (PMID 40051915, 2025). "We speculate that KCTD12 is necessary for the precise timing of GABAB receptor-mediated inhibitory effects on network activity, perturbation of which would manifest as psychiatric disorders." (PMID 23843457, 2013).
KCTD12 also shares sentences with these, for which no sentence is quoted: schizophrenia (2 papers); acute myeloid leukemia (1); alcohol abuse (1); autism (1); cholangiocarcinoma (1); clear renal cell carcinoma (1); diabetes (1); diffuse large B-cell lymphoma (1); endocervical adenocarcinoma (1); esophageal carcinoma (1); glioblastoma multiforme (1); head and neck squamous cell carcinoma (1); lung adenocarcinoma (1); lung squamous cell carcinoma (1); lymphoid neoplasm (1); mantle cell lymphoma (1); movement disorder (1); neurodevelopmental disorder (1); non-small cell lung carcinoma (1); ovarian serous cystadenocarcinoma (1); pancreatic adenocarcinoma (1); paraganglioma (1); pheochromocytoma (1); rectal adenocarcinoma (1); sarcoma (1); septic arthritis (1); thymoma (1); uterine corpus endometrial carcinoma (1); X-linked Emery-Dreifuss muscular dystrophy (1).